MIR7-2 (microRNA 7-2)
Synonyms: hsa-mir-7-2; MIRN7-2; mir-7-2
Gene: MicroRNA gene on chromosome 15 (88,611,825 to 88,611,934, forward strand). Ensembl gene ENSG00000207703.
Gene Ontology:
Biological process: miRNA-mediated post-transcriptional gene silencing
Cellular component: RISC complex
Diseases named in the same sentence as MIR7-2 in open-access papers:
MIR7-2 is named in the same sentence as 2 diseases in open-access papers, as found by Europe PMC text mining. Sharing a sentence is not in itself a finding about the gene and the disease. The quoted sentences say what the papers report.
breast carcinoma (1 paper, 2015). "The transcription factor Forkhead box P3 (FOXP3) which also positively regulates miR-7 expression in breast cancer has been found to have potential binding regions in the locality of MIR7-1 and MIR7-2 genes." (PMID 26308064, 2015).
MIR7-2 also shares sentences with these, for which no sentence is quoted: hepatocellular carcinoma (1 paper).